DNMT1 (DNA methyltransferase 1)
Diseases named in the same sentence as DNMT1 in open-access papers (continued):
Sharing a sentence is not in itself a finding about the gene and the disease.
tumor (continued). "DNMT1 and EZH2 are linked with low tumor-infiltrating CD8+ T cells and poor patient outcomes." (PMID 38715072, 2024). "An increase in pro-apoptotic BCL-2 proteins after a DNMT1 blockade could restore cell death, which tumor cells would otherwise avoid." (PMID 39595939, 2024). "Mechanistically, we propose a functional model wherein DNMT1-remodeled genome-wide DNA hypomethylation patterns regulate oral malignant transformation and tumor growth, through signal collaborations involving PI3K-AKT, CDK2-Rb and GSK3β-mediated glycogen metabolism." (PMID 38755637, 2024). "A reduction in tumor growth was observed after both DNMT1 and PI3K inhibition." (PMID 38755637, 2024). "Furthermore, DNMT1 attenuates the tumor cell-derived Th1-type CXCL9 and CXCL10 expression, which influences effector T cell trafficking into the TME in ovarian cancer." (PMID 38715072, 2024). "These two azanucleosides contain a nitrogen at the C-5 position of their pyrimidine ring that blocks the catalytic activity of DNMTs, resulting in DNMT1 degradation and genome-wide DNA hypomethylation, and facilitating the re-expression of tumor previously silenced by DNA methylation." (PMID 38225241, 2024). "Interestingly, DNMT1-mediated glycogen deposition was abnormally located in apoptotic cells around necrotic tumor areas, accompanied by enhanced glycolysis." (PMID 38755637, 2024). "DNMT1 exhibits unusual activation in tumors and CSCs, playing a pivotal role in mediating the methylation of downstream molecules, thereby inducing self-renewal and tumor growth of CSC." (PMID 38622665, 2024). "Dnmt1 deletion in endothelial cells (ECs) impairs tumor growth while priming expression of cytokine-driven cell adhesion molecules and chemokines important for CD8+ T-cell trafficking across the vasculature; consequently, the efficacy of immune checkpoint blockade (ICB) is enhanced." (PMID 37055433, 2023). "Likewise, loss of miR-342 leads to an increase in DNA methyltransferase 1 (DNMT1), which in turn leads to hypermethylation of several tumor suppressor genes in CRC." (PMID 37373289, 2023). "DNMT1 was inhibited and p21 was up-modulated in these tumor samples." (PMID 37045940, 2023). "Treatment with EZH2 and DNMT1 epigenetic regulators synergistically loosened Th1‐type chemokine repression and promoted effector T‐cell tumor trafficking; thus, ultimately potentiating the therapeutic effect of programmed death‐ligand 1 (PD‐L1) and adoptive T‐cell transfusion." (PMID 36599655, 2023). "Collectively, these studies show important roles for DNMT1 during anti-tumor immunity, but it is unknown how methylation-specific cues in other cell types in the tumor microenvironment might impact tumor immune surveillance and responses to ICB." (PMID 37055433, 2023). "Here we explore the immunoregulatory functions of DNMT1 in the tumor vasculature of female mice." (PMID 37055433, 2023). "Thus, to determine the specific role of Dnmt1 in the vasculature during tumor growth and immune surveillance, we generated a conditional deletion model to ablate Dnmt1 in Cdh5+ ECs (Dnmt1iECKO mice)." (PMID 37055433, 2023). "The inhibition of DNMT1 improved tumor microenvironment and delayed tumor growth." (PMID 37686163, 2023). "Furthermore, combined targeting of mTOR and DNMT1 has been demonstrated to have a more effective tumor suppressive function in HCC." (PMID 37088830, 2023). "In addition, DNMT1 inhibition by specific inhibitors showed tumor regression and increased survival of AML mouse models." (PMID 37573395, 2023). "Similarly, the reduction of CAMK2N1 expression also inhibited the tumor suppressive effect of DNMT1 knockdown." (PMID 36755811, 2023). "The study showed that DNMT1 inhibition reduced tumor size in immunocompetent mouse OSCC models." (PMID 37835379, 2023). "Furthermore, we determined the expression of the members of the DNA methyltransferase family (DNMT1, DNMT3a, and DNMT3b) in tumor tissue by immunohistochemistry." (PMID 37175434, 2023).
tumor (continued). "Similar results were seen in the in vivo tumor xenografts suggesting that hypoxia could be another factor leading to DNMT1 overexpression and hypermethylation in PDAC." (PMID 37759986, 2023). "The results confirmed in vivo the significant reduction of xenograft tumor volume and weight in mice treated with casticin only, or agomir-148a-3p only, the reduction of DNMT1 activity and mRNA levels, and the reduction of the stemness biomarker CD44 expression." (PMID 37304067, 2023). "MGMT and DNMT1 silencing efficiencies in solid tumors by 5-Aza and Lomeguatrib, respectively, were confirmed by Western blot and qRT-PCR with protein and mRNA extracted from tumor tissues." (PMID 37894860, 2023). "Among them, DNMT3b, DNMT1, ALYREF, TET2, NSUN2 and NSUN5 mutations imply that m5C may act abnormally in the tumour." (PMID 37408139, 2023). "This suggests that the observed anti-tumor effect of UHRF1 depletion is, at least partially, mediated by its role in DNA methylation, and that DNMT1 inhibition may mimic the effect of UHRF1 loss." (PMID 37407562, 2023). "Furthermore, the tumor tissues were dissected and RT-qPCR expounded that DNMT1 expression levels were reduced, while those of miR-497 were increased in tumor tissues in the presence of sh-DNMT1 and ADR." (PMID 35255904, 2022). "Indeed, several studies show that epigenetic aberrations such as the loss of DNMT1 protein expression or DNMT1/PCNA/UHRF1 complex integrity are the source of genetic instability (deletion, translocation) and point mutations promoting tumor formation." (PMID 36278678, 2022). "Collectively, DNMT1 has opposite effects on CSCs from different tumor sources." (PMID 35798319, 2022). "Among them, DNMT1 was the first identified, and it is an attractive target for tumour chemotherapy." (PMID 35670075, 2022). "Both compounds depleted DNMT1 and inhibited tumor growth in human tumor xenograft models." (PMID 37077808, 2022). "Moreover, DNMT-1 expression was much higher in LSCC specimens than that in the paired non-tumor tissues and was positively correlated with PSEN-1 and N-cadherin expression, typical downstream factors of Notch pathway-related to EMT." (PMID 35401185, 2022). "Moreover, EZH2 and DNMT1 expression in tumor are negatively correlated with CD8+ T cells tumor-infiltration and patient outcomes." (PMID 36038549, 2022). "In addition, the IHC staining of xenograft tumor tissue demonstrated that the protein levels of DNMT1 and DNMT3B were significantly decreased after ZVI@CMC treatment." (PMID 36310172, 2022). "Inactivation of EZH2 or DNMT1 exerts much immunological relevance, which may affect its anti-tumor therapeutic efficacy while enabling immune-modifying agents." (PMID 36038549, 2022). "Overexpression of DNMT1 could be associated with the development and relapse of AML triggered by hypermethylation of tumour suppressor genes." (PMID 35838271, 2022). "Moreover, HBx acts as an epigenetic deregulator by altering transcription of DNMT1 and 3 and thereby suppresses E-cadherin tumour suppressor while hypermethylating p16 via pRb-E2f pathway." (PMID 35203390, 2022). "Mechanistic studies with epigenetic and transcriptomic profiling showed that MLL4 promotes activation of both typical and super enhancers to increase the expression of their nearby genes, including the RISC component Ago2 and the DNA methyltransferases Dnmt1 and Dnmt3a in tumor cells." (PMID 36323669, 2022). "Importantly, the functional studies showed that the tumour-suppression role of SETD7 is related to its methylation of oncogenic target proteins (Dnmt1, E2F-1 and HIF-1α) leading to their degradation." (PMID 35326563, 2022).
tumor (continued). "This dependency of tumor cells on SLU7 levels to keep cycling, proliferating and surviving could be also associated with its role in maintaining DNMT1 levels and a correct DNA methylation, as DNMT1 silencing induces G2/M arrest and apoptosis." (PMID 36362191, 2022). "In addition, the downregulation DNMT1 induced the low DNA methylation level of cg2406316 of TFF2 in tumor cells." (PMID 36428568, 2022). "In addition, we found that DNMT1 was highly expressed in tumour tissues compared with normal tissues in a tissue microarray (TMA) and that it was positively correlated with many TME-infiltrating immune cells." (PMID 34589490, 2021). "Phosphatase and tensin homolog (PTEN), a well-known tumor-suppressor, has been reported to be hypermethylated by DNA methyltransferase 1 (DNMT1) in EC, while silencing DNMT3a can restore the expression of PTEN, thereby suppressing hepatocellular carcinogenesis." (PMID 34249684, 2021). "DNMT1 and DNMT3B may be useful epigenetic markers in this tumor, indicating their aggressiveness, BRAFv600e mutation, and recurrence chances." (PMID 35048062, 2021). "This study demonstrates that, given the heterogeneous expression of p62 in subclones within a tumor, combined inhibition of epigenetic modifiers (DNMT1 and HDAC1) reversed the histone pattern and increased p62 expression, which significantly improved the sensitivity to radiation of HN9-R clones." (PMID 33674559, 2021). "Such opposing effects of DNMT1 reduction were observed in different tumor models." (PMID 33310759, 2021). "Interestingly, similar findings were reported by others, who associated the aberrant DNA methylation found in UL with an increased DNMT1 and DNMT3a mRNA expression in tumor samples compared to myometrium." (PMID 34233687, 2021). "In the present study, we found that TUG1 showed low expression levels in DNMT1 high-expression cells suggesting that TUG1 may be a tumor suppressor in this system." (PMID 34660799, 2021). "Finally, we demonstrated that fenofibrate administration inhibited tumor growth and DNMT1 activity in vivo." (PMID 33959155, 2021). "SGI-1027 may inhibit DNMT activity, induce the degradation of DNMT1 and reactivate tumor suppressor genes." (PMID 34452630, 2021). "MiR-340 is a recently recognized tumor suppressor which targets and decreases expression of DNMT1, EZH2 and H3K27me3, leading to promoter hypomethylation and expression of E-cadherin as well as decreased expression of mesenchymal markers (N cadherin, vimentin and fibronectin) in TNBC cells." (PMID 33572395, 2021). "Thus, we investigated DNMT1 protein levels before tumor onset and in different tumor stages from tumor-free to end-term tumors in NPM-ALK transgenic mice in comparison to 18-wk-old wild types." (PMID 33310759, 2021). "DNMT1 belonged to the DNA methyltransferase family, and its overexpression is identified in human T-cell, B-cell, and myeloid malignancies, indicating that DNMT1 may play a crucial role in tumor maintenance." (PMID 34840568, 2021). "MiR-148a-3p and DNMT1 form a regulatory pathway that increases tumor proliferation." (PMID 33441699, 2021). "Compared with other DNA methyltransferases (such as DNMT3A), DNMT1 subtypes are not susceptible to mutation and are more suitable as targets for anti-tumor drugs." (PMID 34073721, 2021). "Finally, riluzole was shown to downregulate DNA (cytosine-5-)-methyltransferase (DNMT1), a factor responsible for hypermethylation of tumor suppressors." (PMID 33919596, 2021). "Co-inhibition of EZH2 and DNMT1 in a tumour may have the potential to reprogram the immune microenvironment and increase the efficacy of PD-L1 checkpoint blockade therapy." (PMID 33669182, 2021). "A recent study suggested that CDK4/6 inhibitors could downregulate DNMT1 expression in Treg cells and trigger anti‐tumor immunity, suggesting that targeting PAX6 might be of clinical value to tumor immunotherapy in the future." (PMID 34459131, 2021).
tumor (continued). "We also used the well-known DNMT1 inhibitor 5-aza45 to address whether DNMT1 regulates cell surface HLA-G expression of tumor cells and evaluated its effect on subsequent CAR-NK challenge." (PMID 34663641, 2021). "IL-6 via IL-6R/STAT3 pathway regulates DNMT1 expression in tumor cells." (PMID 33604794, 2021). "To explore the DNMT1 related clinical characters, we determined whether gender, age, race, tumor stage, tumor grade, nodal metastasis, and human papillomavirus (HPV) infection status correlated with DNMT1 expression in HNSCC." (PMID 33500531, 2021). "DNMT1 is required in maintaining CpG methylation and silencing of various tumor suppressor genes." (PMID 34150611, 2021). "Finally, we evaluated the effect of the DNMT1/miR-378a-3p/TRAF1/p65 axis on tumor growth and angiogenesis in vivo." (PMID 34749775, 2021). "Taken together, these results suggest that the tumor PD-L1 level is directly regulated by DNMT1." (PMID 32079180, 2020). "Furthermore, recent studies have revealed that DNMT1 maintains promoter hypermethylation of tumor-suppressor microRNAs." (PMID 32308683, 2020). "Moreover, the CG methylation in the Nanog promoter was also investigated when DNMT1 expression was modulated in tumor cells." (PMID 32154082, 2020). "Enhanced miR-342 expression inhibits cell proliferation and invasion; miR-342 overexpression leads to demethylation and induction of tumor suppressor genes through blocking DNMT1 expression; miR-342 overexpression inhibits tumor growth and lung metastasis in vivo." (PMID 32906681, 2020). "However, we found that the epigenetic control of tumor PD-L1 via DNA methyltransferase 1 (DNMT1) significantly influenced the response to chemotherapy." (PMID 32079180, 2020). "Moreover, DNMT1 represses the tumor production of T helper 1 (TH1)-type chemokines CXCL9 and CXCL10 and the impacts on effector T-cell trafficking into the tumor microenvironment." (PMID 32708698, 2020). "Here, a significantly decreased expression of Dnmt1 and Dnmt3b was recorded early after tumor cell implantation, which indicates a reduced DNA-methylating activity and could explain the increased expression of EdnrB and/or Ece1 mRNA." (PMID 32194414, 2020). "Moreover, the inhibition of DNMT1 activity not only upregulated the PD-L1 level but also remodeled the immunogenicity within the tumor microenvironment in vitro and in vivo." (PMID 32079180, 2020). "Therefore, RCC2 plays a vital role in tumor proliferation, tumorigenicity, and promotes radioresistance by activating transcription of DNA methyltransferase 1 (DNMT1) through a p-STAT3 dependent pathway." (PMID 33521058, 2020). "Loss of Dnmt1 delays lymphomagenesis and leukemogenesis by suppressing normal hematopoiesis and impairing tumor cell proliferation and leukemic stem cell self-renewal." (PMID 32806509, 2020). "Interestingly, DNMT1 expression correlated with cardia or body of the stomach localization of the tumor, DNMT3A expression correlated with TNM score, and their co-expression showed a correlation with lymph-node metastasis." (PMID 32752096, 2020). "Finally, the effects of altering DNMT1 levels in T-cells seemed to affect tumor growth through alteration of methylation status of Foxp3 on promoter and CpG regions." (PMID 31006654, 2019). "Thus, miR-484, who is downregulated by DNMT1-mediated hypermethylation in its promoter, functions as a tumor suppressor by inhibiting MMP14 and HNF1A expression in CC." (PMID 31810492, 2019). "Besides, in hormone refractory prostate cancers, the tumor cells presented drug resistance and increased the expressions of DNMT1 and DNMT3b." (PMID 31771617, 2019). "Treating with EGCG (5–50 μM, for 12–144 h) on human EC cells (KYSE 510) was able to suppress DNMT1 activity, leading to concentration- and time-dependent reversal of hyper-methylation and reactivation of several tumor methylation-silenced genes (p16, RARβ, hMLH1 and MGMT)." (PMID 30857144, 2019).
tumor (continued). "Alternatively, DNMT1 mutant clones could be selected during tumor evolution due their ability to promote carcinogenesis through the senescence-associated secretory phenotype." (PMID 30897760, 2019). "Furthermore, we recently reported that MYC deregulates the expression of methylation modifiers, DNMT3B and DNMT1, essential for tumor maintenance." (PMID 31266538, 2019). "Furthermore, ectopic expression of DNMT1 activated primary normal breast fibroblasts and promoted their pro-carcinogenic effects, both in vitro and in orthotopic tumor xenografts." (PMID 29416775, 2018). "Except for few being chromatin regulators (CGBP, MBD2, and DNMT1), all of these TFs were found to have tumor suppressor functionality (BRCA1, E2F1&2&5&7, EGR1-4, FLI1, NRF1, TFDP2, and STAT1), or indirectly mediate the suppression of tumorigenesis and tumor suppressor activity (SP4 and ZBTB33)." (PMID 29740534, 2018). "Moreover, treatment with 5-AZA, a potent DNMT1 inhibitor, or with the CCR5-antagonist MVC slowed GC tumor xenograft growth, revealing the antitumor effects of DNMT1 suppression by the inhibition of CCR5 engagement in GC." (PMID 29772686, 2018). "Phosphorylation of RELA/p65 promotes DNMT-1 to represses BRMS1 tumor metastasis." (PMID 29467412, 2018). "In fact, in many cancers, promoters of tumor suppressor genes are silenced by hypermethylation at CpG sites, and thus, the inhibition of DNMT-1 could potentially reverse tumor growth." (PMID 30373208, 2018). "(C) The correlation of OPN and DNMT1 in tumor tissues (data form TCGA)." (PMID 30064482, 2018). "In colon tissue of responders, DNMT1 expression (tumours) and p16 promoter methylation (tumours and adjacent normal tissue) were significantly reduced at the end of the study compared with baseline levels, whereas no changes were detected in the three non-responding patients." (PMID 29685968, 2018). "The availability of this natural product could hamper tumor cell metabolic reprogramming by targeting DNMT1." (PMID 29795311, 2018). "Moreover, it is very interesting that OPN related tightly to DNMT1 only in the tumor tissue with grade four and macro vascular invasion in TCGA database." (PMID 30064482, 2018). "Moreover, Qu has also been shown to inhibit cell cycle and induce apoptosis through inhibition of HDAC and DNMT1, thus suppressing tumor growth and angiogenesis in an induced model of hamster buccal pouch carcinoma." (PMID 30409182, 2018). "The mechanisms for such elevation are still unclear, but overexpression and activation of DNMT1 or other forms of DNMTs may result in promoter hypermethylation of multiple tumor suppressors, thus ultimately leading to poor prognosis and lung tumorigenesis." (PMID 28427182, 2017). "Thus, HMA appears to have to inhibit DNMT3a and DNMT3b as well as DNMT1 to exert anti-tumor activities." (PMID 28052028, 2017). "Complementary to these findings, the results of our study implied that DBCCR1 suppression and DNMT1 activation could be synergistically induced during tumor progression via positive feed-forward mechanisms." (PMID 28427182, 2017). "Many studies have indicated that the overexpression of DNMT1 could silence vital tumor suppressor genes such as APC, P16, and RUNX3 through DNA methylation." (PMID 28473984, 2017). "In addition, DNMT1 also involves in various biological functions, including tumor growth and progression." (PMID 28360411, 2017). "Moreover, the differential expression of Hells and Dnmt1 suggests a crucial role of DNA methylation in tumor development." (PMID 28212608, 2017). "In vivo study showed silencing DNMT1 suppressed tumor growth in nude mice." (PMID 27286455, 2016).